FHIT (fragile histidine triad diadenosine triphosphatase)
Diseases named in the same sentence as FHIT in open-access papers (continued):
Sharing a sentence is not in itself a finding about the gene and the disease.
cancer (continued). "Our lab has shown that loss of FHIT expression causes genome instability and provides single-strand DNA substrates for APOBEC3B hypermutation, in line with evidence that FHIT locus deletions occur in many cancers." (PMID 29254236, 2017). "Our results confirmed that the cfDNA level and methylation of CpG islands of RASSF1A, FHIT, and APC genes in blood plasma can be used as noninvasive diagnostic markers of cancer." (PMID 27725787, 2016). "The positive expression rate of FHIT in the cancer tissues of the OCFH + patients (46%; 15/33) was significantly lower than that of the OCFH − patients (73%; 30/41), and the difference was statistically significant (P<0.05)." (PMID 25436004, 2015). "Previous studies demonstrated that the FHIT 5′ promoter region was partially methylated in certain human cancer cell lines." (PMID 24396396, 2014). "Fragile histidine triad (FHIT) is a tumor suppressor protein that regulates cancer cell proliferation and apoptosis." (PMID 24757411, 2014). "Recently, it has been shown that FHIT loss also affects EMT, considered a crucial step in the early stage of cancer metastasis." (PMID 25340791, 2014). "While vulnerable to DNA damage itself, FHIT protein expression is essential to protect from DNA damage-induced cancer initiation and progression by modulating genome stability, oxidative stress and levels of accumulating DNA damage." (PMID 24901304, 2014). "The FHIT gene is positioned at one of the most active CFSs, FRA3B, and is one of the most frequently altered genes in preneoplasia and cancer." (PMID 24901304, 2014). "Two cancer genes including FHIT (collocated with FRA3B) and PDGFRA (collocated with FRA4B) that topped the concurrent LOH list in SNP array based analysis also show high levels of concurrent LOH in the sequencing based analysis." (PMID 24748104, 2014). "The FHIT gene was characterized as a cancer suppressor soon after it was cloned in 1996, though there was not universal agreement concerning its suppressor role." (PMID 24901304, 2014). "This review discusses the relationship between FHIT, reactive oxygen species production, and DNA damage in the context of cancer initiation and progression." (PMID 24901304, 2014). "A number of studies have indicated that the Fragile Histidine Triad (FHIT) gene product, FHIT, functions as a tumor suppressor in a variety of common human cancers." (PMID 25340791, 2014). "Genetic alteration of FHIT and nearby genomic region and its involvement in renal disease (carcinoma) is very well documented." (PMID 25478860, 2014). "The FHIT tumor suppressor gene is arguably the most commonly altered gene in cancer since it is inactivated in about 60% of human tumors." (PMID 23947369, 2013). "Despite the extensive analysis of FHIT gene in cancer cells, the studies on primary malignant tissues are limited." (PMID 22295218, 2011). "Although FHIT protein expression is lost or reduced in many types of human cancers, the mechanistic basis for the involvement of intron 5 in genetic risk of prostate cancer is not apparent." (PMID 18953408, 2008). "Immunohistochemical analysis in primary cancer tissue confirmed the absence or greatly reduced expression of FHIT protein levels in tumor cells, in contrast to high levels of expression in the adjacent normal prostate epithelium." (PMID 18953408, 2008). "Abnormal expressions of the FHIT gene are connected to diverse forms of malignant tumor development." (PMID 18366613, 2008). "In some carcinomas with highly malignant degree, FHIT protein is deleted; in the carcinomas with lower malignant degree, FHIT protein not completely deleted but reduced." (PMID 18366613, 2008). "The recent publications on frequencies of FHIT methylation in human cancer have been tabulated as references for those readers particularly interested in studying FHIT." (PMID 16928264, 2006). "Some studies have shown that the simultaneous loss of expression of FHIT and WWOX is frequent in several cancers." (PMID 16895604, 2006).
cancer (continued). "Additional studies have confirmed that the FHIT gene is abnormally expressed in 30–78% of cervical dysplasia, carcinoma cell lines, and primary tumors." (PMID 16248899, 2005). "We examined the hypermethylation status of a panel of 5 normally unmethylated tumor suppressor or cancer genes: FHIT, FANCF, Cyclin-D2, BRCA2 and RUNX3 in 25 ovarian GCTs and ovarian cell line DNAs using the MSP assay." (PMID 15574200, 2004). "Loss of heterozygosity (LOH) analysis demonstrated that the abnormal FHIT transcripts found in cancer cells were attributable to abnormalities of the FHIT gene." (PMID 10732756, 2000). "Because of the characteristics of CFSs, it was previously thought that deletions at the FRA3B locus found in many cancers were simply passenger events rather than a cause of loss of FHIT function." (PMID 38069335, 2023). "In early lesions of many types of cancer, the FHIT protein inactivation induces replication stress." (PMID 36831487, 2023). "FHIT is a known tumor suppressor gene and is downregulated in various human cancers." (PMID 38069335, 2023). "The corresponding deletion of the FHIT protein after FRA3B deletion may predict malignant tumor formation." (PMID 36831487, 2023). "Interestingly, most of these common candidates are large cancer genes within fragile sites, such as FHIT, WWOX, CCSER1, IMMP2L, CDKN2A, and CDKN2B26,44–47." (PMID 36163358, 2022). "In cancer, focal deletions are often associated with CFS; in a pan-cancer analysis of 4934 cases, 70 recurrent focal deletions were reported, of which 22 were found in large genes and several genes known from CFS regions (FHIT, WWOX, PDE4D, PARK2)." (PMID 35563471, 2022). "A number of these genes are not only known to be involved in the predisposition of several cancers (CDKN2A, POT1, FHIT) but are also associated with immune traits (monocyte, platelet, etc.), cholesterol, high density lipids/light density lipids, and allergens in humans." (PMID 33793571, 2021). "The FHIT gene encompasses the FRA3B locus, a common fragile site deleted in cancer." (PMID 34092254, 2021). "Furthermore, the FHIT gene was found to span the FRA3B common chromosomal fragile site and aberrant transcripts of the FHIT gene were found in cancer cells." (PMID 34210081, 2021). "Due to FHIT’s location, deletions within FHIT are common in cancer." (PMID 34092254, 2021). "Loss of FHIT expression would allow a favorable environment for HTLV-I infected cells to obtain cancer driver events, in the absence of high levels of Tax expression." (PMID 34092254, 2021). "Among the genes reported to be altered in a genome-wide methylome analysis, we selected FHIT as a potential candidate for an ATL predisposition factor because of its essential role in preserving genome integrity and its frequent inactivation in human cancers." (PMID 34092254, 2021). "In another study, replacement of FHIT protein in cancer cells suppressed their tumorigenicity." (PMID 34210081, 2021). "However, it has been recently reported that this signature is dominant in Fhit knockout mice and in cancer samples of The Cancer Gene Atlas that display FHIT gene deletion, suggesting a direction for future research on this topic." (PMID 30657883, 2019). "Besides, the expression level of the FHIT gene is relatively low in comparison with other functional genes in cancer." (PMID 28036263, 2017). "FHIT is a genome caretaker/tumor suppressor that is silenced in >50% of cancers." (PMID 29282095, 2017). "Signature 5 mutations were found in all cancer types studied in this report, including the cancers of the nonsmokers, as expected for cancers with FHIT loss." (PMID 29254236, 2017). "In addition, we also detected the methylation status of FHIT promoter in other kinds of cancers using TCGA datasets for further validation, and similar results were obtained and showed limited diagnostic ability." (PMID 28036263, 2017). "FHIT protein was more expressed in intestinal-type than diffuse-type carcinomas (p < 0.00001)." (PMID 29296239, 2017).
cancer (continued). "FHIT is genetically or epigentically altered in many primary and advanced carcinomas." (PMID 26796853, 2016). "Indeed, the FRA3B CFS is frequently found as site of translocations in cancer, resulting in the inactivation of the FHIT tumor suppressor gene that localizes at this site." (PMID 25753673, 2015). "Epigenetic silencing of FHIT has been observed in several human cancers." (PMID 25460508, 2015). "Although there are suggestions of a role for FHIT loss in progression of various cancers, a role for such loss in metastasis has not been defined." (PMID 25340791, 2014). "FHIT is altered in many different kinds of primary or advanced carcinomas." (PMID 24757411, 2014). "Also, the successful FHIT gene therapy in a series of preclinical models of human cancer makes Fhit protein a good candidate for the search for innovative therapies." (PMID 24223161, 2013). "We speculate the role of FHIT in inhibiting malignant transformation, however, we will further investigate FHIT in our research to prevent cancer development." (PMID 18366613, 2008). "Furthermore, the bioinformatics studies showed diversiform human epithelial malignancies, FHIT gene absence, abnormal methylation and deplete of FHIT protein express level contribute 70% of human cancers relating the functionality of FHIT." (PMID 18366613, 2008). "A germ-line alteration in FHIT that is associated with cancer risk has not been reported, possibly because of limitations of previous studies that focused only on exons, untranslated regions of mRNA, and promoters." (PMID 18953408, 2008). "FHIT gene-coding protein is a carcinoma suppressor, it can lead microtubule assembly; however, it can also suppress cell cycle, and may trigger cell apoptosis." (PMID 18366613, 2008). "Since frequent LOH is a hallmark of genomic instability and commonly used as a genetic marker for cancer, we aimed to conduct microsatellite analysis for allelic deletion of FHIT locus for examining the genetic mechanism of allelic deletion with loss of Fhit protein expression." (PMID 15150628, 2004). "The loss of FHIT protein expression was not correlated with any of the markers of cancer progression studied." (PMID 15570308, 2004). "FHIT gene structure and protein expression have been examined in detail in many types of cancers." (PMID 15494723, 2004). "Aberrant FHIT transcripts were observed in 5/33 carcinomas (15%) and in 1 of 2 borderline tumours." (PMID 11461085, 2001). "Although most mutations in cancer are “passengers” and do not critically affect the process of cancer evolution and development, the positive selected mutations frequently caused by abnormal FHIT expression tend to be a “driver”." (PMID 36831487, 2023). "Thus, the role of the FHIT is indispensable in Cancer Evo-Dev." (PMID 36831487, 2023). "For other cancers, FHIT may be inactivated through other means." (PMID 35663592, 2021). "To address this question, we investigated the presence of APOBEC3B-like mutational patterns and mRNA expression of the APOBEC3A, APOBEC3B, UNG, REV1, and FHIT genes in cancer cell lines, in order to identify those cancer cell lines that may have experienced kataegis events." (PMID 29642934, 2018). "Reportedly, FHIT down-regulation or loss might be due to its promoter methylation and loss of heterozygosity in cancers, but not its gene mutation." (PMID 29296239, 2017). "Among all tested cancer genes, whether deleted, amplified or mutated, IDH1 was the only one with negative log2 odds ratio, i.e. it was mutually exclusive of FHIT deletion, meaning that cancers with significantly mutated IDH1 genes do not show FHIT allele loss." (PMID 29254236, 2017). "Therefore, FHIT replacement or therapeutic activation of the FHIT pathway could contribute to cancer prevention." (PMID 25880193, 2015).
cancer (continued). "More in detail, chromosomal fragile sites FRA3B and FRA16D, carrying the FHIT and WWOX genes respectively, that are genes playing a major role in apoptosis, show correlated expression and association with failure of apoptosis in lymphocytes from cancer patients." (PMID 25860149, 2015). "However, the role of FHIT in the radioresistance of human cancers is less explored." (PMID 25460508, 2015). "The results indicate that these effects of FHIT could in part be mediated by FHIT-regulated miRNAs, pointing to miRNAs as crucial factors in the metastatic process, and as possible therapeutic targets in cancer." (PMID 25340791, 2014). "However, the FHIT gene is considered as a carcinoma suppressor gene." (PMID 18366613, 2008). "In a study of OSCCs associated with betel and/or tobacco use, 28% of samples exhibited FHIT promoter methylation, and 36% of cancers and 50% of premalignant lesions showed aberrant RT–PCR products, suggesting that FHIT aberration could be an early event in oral carcinogenesis." (PMID 12771912, 2003). "The Fragile histidine triad gene (FHIT) maps to a chromosome 3 region called FRA3B, which is one of the most fragile of the common fragile sites (CFSs) in human cancers." (PMID 38069335, 2023). "miRNAs play direct or indirect roles in regulating oncogenes (KRAS), tumor suppressor genes (FHIT, WWOX), and immune-related gene (TLR8), which ultimately promote cancer cell growth and dissemination." (PMID 34470640, 2021). "Intronic HPV breakpoints in FHIT and LRP1B have been related to decreased protein expression in carcinoma samples." (PMID 33810183, 2021). "There were several established cancer genes involved in a total of 12 common CNAs identified according to GISTIC, including EGFR, CCND1, FHIT, and FAT1." (PMID 31159251, 2019). "While 26 tumors and 243 cancer cell lines have a breakpoint in FR3B, the majority of these breakpoints, namely 23 and 223, lay in the FHIT gene." (PMID 31249626, 2019). "Examination of gene expression measures in the pan-cancer dataset showed a bimodal distribution of APOBEC3B expression, whereas APOBEC3A, REV1, UNG, and FHIT had unimodal distributions of their expression measures." (PMID 29642934, 2018). "Using bisulfite treatment followed by MS-PCR we detected methylation of the LRRC3B, APC, FHIT, and RASSF1 genes in the cfDNA of cancer patients." (PMID 27725787, 2016). "The FHIT, BRCA2 and MLH1 expression levels were identified to be significantly lower in the cancer tissues from OCFH + patients." (PMID 25436004, 2015). "Recurrent alterations have been identified in FRA3B and FRA16D in several cancer types, leading to further investigation of the FHIT and WWOX genes, respectively, in mouse models (see K. Huebner and R. Aqeilan chapters in this issue)." (PMID 25238782, 2014). "Additional studies are required to examine the clinical relevance of impairments in the expression and function of FHIT with respect to HCC and other types of human cancer." (PMID 24396396, 2014). "Several genomic regions containing fragile sites, such as the FHIT gene locus at 3p14.2, RBFOX1 at 16p13.3 and MACROD2 at 20p12.1 that were targeted for deletion in MSS cancers, were also relatively commonly deleted in BRAFmut/MSI cancers." (PMID 24651849, 2014). "In conclusion, genetic mutation in the Kras gene and epigenetic modification in RASSF1A, FHIT and MGMT genes in sporadic CRC are associated with the overall development of the disease and may be used as diagnostic or prognostic markers in this group of cancers." (PMID 23573237, 2013). "Six of these genes (FHIT, TMSL3, PARK2, A2BP1, MACROD2 and MAP2K4) have been consistently reported as deleted in CRC and other cancers." (PMID 24367615, 2013).
cancer (continued). "It follows from a comprehensive statistical analysis that a number of antigens such as hTERT, PCNA and Ki-67 can be considered as cancer markers, while another set of antigens such as P27KIP1 and FHIT are possible markers for normal tissue." (PMID 18366613, 2008). "Moving down to the oesophagus, FHIT LOH and Fhit expression were studied in precarcinomatous lesions and carcinoma." (PMID 12771912, 2003). "Synergic action between the FHIT and APOBEC3B in cancer has been observed in several cancers." (PMID 36831487, 2023). "In addition, we have identified large genes residing in common fragile sites to be significantly affected by deletions and contributing to cancer development, including CSMD1, WWOX and FHIT." (PMID 36726722, 2022). "Compared to Del-c1 and c3, the majority of cancer genes were deleted by DEL-c2, such as CDKN2A (207/528), FHIT (133/528), KDM6A (42/528), RB1 (27/528), FAT1 (23/528), NFE2L2 (13/528), ERBB4 (20/528), CUL3 (11/528), PTEN (9/528), ZNF750 (13/528) and NOTCH1 (8/528)." (PMID 36272974, 2022). "For example, FHIT, CSMD1, and LRP1B have been reported in cancer and lesions." (PMID 33810183, 2021). "Considering that FHIT knockout did not fully abolish tanshinones’ anti-cancer function, there should be multiple targets in multiple steps involved to the effects of tanshinones inhibition of tumor progression." (PMID 34108553, 2021). "The lack of FHIT protein or its reduced level is observed in many types of cancer as well as in various cancer cell lines." (PMID 33920347, 2021). "FHIT (3p14.2) encompasses FRA3B and encodes for a tumor suppressor gene: its inactivation is reported in many cancers, even if the exact mechanism is as yet not completely understood." (PMID 32759723, 2020). "There appeared a negative relationship between FHIT mRNA expression and the progression-free survival rate of T4 cancer patients (p < 0.05)." (PMID 29296239, 2017). "Likewise, FHIT and WWOX deletions within fragile sites FRA3B (most frequently expressed) and FRA16D, respectively, have been observed in many cancers." (PMID 26337081, 2015). "The negative expression rates of FHIT in the well−, moderately, and poorly differentiated carcinoma tissues were 40% (4/10), 38% (18/48) and 44% (7/16), respectively." (PMID 25436004, 2015). "Due to the critical involvement of microRNAs (miRNAs) in cancer metastasis and EMT, we next determined if FHIT might regulate expression of specific miRNAs." (PMID 25340791, 2014). "The BRAFmut/MSI cancers had substantially fewer MCRs than the MSS cohorts, however they did have a comparatively high proportion of cancers (≥20%) with focal deletions at 3p14.2 (FHIT), 16p13.3 (RBFOX1) and 20p12.1 (MACROD2)." (PMID 24651849, 2014). "It was determined that FRA3B (FHIT) and FRA16D (WWOX) loci rank second and third respectively, only after the CDKN2A (p16) locus, as the chromosomal sites most commonly affected by hemi- and homozygous deletions in a genome wide study of over 740 cancer lines." (PMID 24330518, 2013). "To determine if Fhit suppresses formation of DSBs in cancer cells, we used endogenous Fhit-negative H1299 lung adenocarcinoma cells carrying either an inducible FHIT cDNA expression plasmid (D1 clone) or the empty vector control (E1 clone)." (PMID 23209436, 2012). "It suggests that sometimes FHIT protein in malignant carcinoma is not completely deleted but reduced." (PMID 18366613, 2008). "This could include the establishment of FHIT underexpression in a subset of proliferative BBD lesions and carcinomas." (PMID 17164758, 2007). "Full length FHIT transcripts were not detectable in nine lesions (two cancers, five CIN3 and two CIN1)." (PMID 11875703, 2002). "However, FHIT methylation has not been shown to be dependent upon patient age or gender in any other cancers suggesting this is also the case in ATL." (PMID 34092254, 2021).